CDK4 (cyclin dependent kinase 4)
Diseases named in the same sentence as CDK4 in open-access papers (continued):
Sharing a sentence is not in itself a finding about the gene and the disease.
tumor (continued). "In high PDIA3 expression samples, frequently amplified genomic peaks were detected in oncogenic drivers, including PDGFRA, EGFR and CDK4; in addition, tumor suppressor genes, such as CDKN2A/CDKN2B and PTEN were observed a deletion peak." (PMID 32687065, 2020). "In tumor cells, CDK4/6 inhibitors suppressed the RB-E2F-DNMT1 axis, which activated endogenous retroviral elements and increased double-stranded RNA levels." (PMID 32933570, 2020). "It has been demonstrated that cancer cell senescence induced by CDK4/6 inhibition can promote the development of more aggressive drug-resistant cancer stem cells leading to attenuated response to anti-tumor agents and cancer recurrence." (PMID 33213401, 2020). "In the further study, we found that co-treatment with baicalin and Akt activator SC79 significantly attenuated the decreased tumor size and upregulated the expression of p-Akt, p-mTOR, CDK4, and Cyclin E2, when compared with baicalin treatment alone." (PMID 33585556, 2020). "Taken together, these data suggest tumour rewiring leading to increased ERBB/MAPK signalling influences sensitivity to CDK4/6 inhibition." (PMID 32307447, 2020). "PI3K-AKT-mTOR and RAS-RAF-MEK-ERK pathway inhibitors both exhibit synergistic tumor suppression effects with CDK4/6 inhibitors in many preclinical models." (PMID 32933570, 2020). "CDK4/CDK6 inhibitor palbociclib reduces tumor growth by reducing retinoblastoma (RB) protein phosphorylation and cell cycle arrest, which induces G1/S phase transition." (PMID 32508030, 2020). "Accordingly, our analysis of a subset of genes that had a significant Z score for similarity to proliferation of tumor cells predicted cell cycle progression through genes such as CDK4, HRAS, IL-4, CSF2, IFNG, IL-6 and STAT3." (PMID 33180876, 2020). "Highly selective and potent small-molecule CDK4/6 inhibitors have shown anti-tumor activity both in vitro and in vivo." (PMID 32624705, 2020). "Although IR recruits regulatory T cells (Treg) and other immunosuppressive cells to the tumor microenvironment, CDK4/6 inhibitors markedly reduce the proliferation of Tregs." (PMID 32933570, 2020). "As cell cycle regulators, CCND1 and CDK4 play critical roles in regulating the cell cycle of normal and tumor cells." (PMID 32742488, 2020). "Mouse tumor tissues were sectioned and subjected to immunohistochemical staining to analyze the expression of class I HDACs and p21, CDK4, cyclin D1, Ki-67, and EMT-related genes." (PMID 32850418, 2020). "Collectively, these results indicate that GSK3β-mediated regulation of cell cycle progression via cyclin D1, CDK4 and cyclin B1 is responsible for tumor cell survival and proliferation in ESCC." (PMID 32678196, 2020). "Subsequent in vivo studies establish that the Cyclin D1/CDK4 axis plays a critical role not only in glial tumor cells but also in stromal-derived cells, which sustain tumor growth." (PMID 33317149, 2020). "CDK4/6 promote the cell cycle G1/S transition by phosphorylating the retinoblastoma (Rb) protein, the gene product of a tumor-suppressor gene, and a central regulator of cell cycle progression." (PMID 32483149, 2020). "The CDK4/6-RB integrated signature developed herein behaves in a highly consistent fashion across all tumor types analyzed, suggesting that this gene expression module is essentially invariant." (PMID 32242058, 2020). "The analysis of CCA tumor samples employing TCGA database indicated CDK4 and CDK6 overexpression versus normal samples." (PMID 33116269, 2020). "CDK4/6 inhibition increased PD-L1 levels and markedly enhanced tumor regression and improved overall survival in combination with anti-PD-L1 immunotherapy in murine tumor models." (PMID 32486375, 2020). "Among the potential drug targets, we identified some well-known targets, including EGFR, ERBB2, and PARP1 as well as CDK2 and CDK4/6, which are related to the regulation of tumor cells development." (PMID 33287876, 2020).
tumor (continued). "In agreement with our results, non-protective autophagy does not seem to be essential for the generation of senescent cells exhibiting dysregulated lysosomal biogenesis, as when when tumor cells are induced into senescence by CDK4/6 inhibitors." (PMID 32093197, 2020). "Western blotting showed that E2F4 knockdown promoted the expression of CD11b and CD14 and inhibited the expression of cyclin D1, cyclin A2, P‐Rb and CDK4 compared with the expression in control tumours." (PMID 31943751, 2020). "At present, the therapeutic focus has been on leveraging CDK4/6 inhibition to activate RB and limit proliferation of tumor cells to delay disease progression." (PMID 32242058, 2020). "In normal cells, CDK4/6 is rigorously regulated by members of the INK4 CDK inhibitor family; however, genetic changes or overexpression of cyclin D1-3, CDK4/6, and INK4 family members cause the cell cycle to become dysregulated, resulting in tumor formation." (PMID 33271970, 2020). "Future investigations using tumor-infiltrating lymphocyte analyses are needed to better understand CDK4/6 inhibitor resistance mechanisms of immune evasion." (PMID 33364954, 2020). "Currently, they are also under investigation in phase I and II clinical trials on other solid tumors and in patients with amplification or overexpression of CDK4 at tumor level (NCT03242382)." (PMID 32373071, 2020). "Despite the clinical benefit of CDK4/6 inhibitors, tumour resistance develops in most patients in the metastatic setting and finding new therapeutic targets for these patients remains an unmet clinical need." (PMID 32792481, 2020). "Taken together, FBX8 regulates the biological function dormant tumor cells by maintainning tumor cell stemness and targeting C-Myc, CDK4, and HIF-1α." (PMID 32796813, 2020). "Previous in vitro data have objectified the activity of CDK4/6 inhibitors on luminal-HER2 type tumor cells, i.e., expressing both ER and HER2." (PMID 32545895, 2020). "P16, a tumor suppressor, can prevent the cells from entering the S phase by inhibiting the activity of CDK4 and has become an important target for the development of antitumor drugs on cell cycle inhibition." (PMID 33628179, 2020). "Recently, small inhibitors of CDK4/6 have been used for restraint of tumor progression through induction of cell cycle arrest." (PMID 31824858, 2019). "In particular, RTK/PI3K-Akt pathway inhibitors and CDK2 inhibitors have been evaluated in combination with CDK4/6 inhibitors very detailed in other tumor entities before." (PMID 31331377, 2019). "Taken together, these data demonstrate the anti-tumor activity of elacestrant in clinically relevant CDK4/6i-resistant models in vitro, as well as inhibition of ER signaling and growth, regardless of sensitivity to CDK4/6i and ESR1 mutational status." (PMID 31852484, 2019). "We demonstrate in multiple models of CDK4/6i resistance that elacestrant exhibited anti-tumor activity and this activity was observed despite each resistant model exhibiting differential modulation of key cell cycle proteins." (PMID 31852484, 2019). "Due to the importance of CDK4/6 activity in tumorigenesis, targeted inhibitors of the CDK4/6 gene have become new candidates for tumor therapy." (PMID 32117430, 2019).
tumor (continued). "This in turn stimulates the production of type III interferons and therefore enhances the tumor antigen presentation; second, CDK4/6 inhibitors markedly suppress the proliferation of regulatory T-cells." (PMID 31336685, 2019). "Collectively, these results strongly support the notion that, in cancer, CDK4/6 inhibition not only halts the cancer cell cycle but also promotes T cell-dependent anti-tumor activities in combination with ICI." (PMID 30863749, 2019). "The CDK4/6 inhibitor not only acts on tumor cells but also acts indirectly and directly on the immune cells responsible for antitumor immunity." (PMID 30863749, 2019). "p16 is well known to bind CDK4/6, inhibit the cyclin D-CDK4/6 complex, negatively regulate cellular proliferation, and positively inhibit tumor formation." (PMID 31327760, 2019). "Other tumour samples showed expression of CDK4, CDK6, and p-Rb protein but also p16 expression, which is associated with ineffectiveness of palbociclib, and these patients were therefore regarded as potential nonresponders." (PMID 30804704, 2019). "Taken together, these data indicate that CDK4 aberration dictates the sensitivity of MM-derived PDX tumor growth to CDK inhibitors." (PMID 31358010, 2019). "Inhibition of CDK signaling pathway and CDK4 signaling pathway alone obviously suppresses the proliferation of MM cells and the tumor growth in PDX models harboring CDK4 pathway abnormity." (PMID 31358010, 2019). "A series of recent independent investigations has demonstrated a critical cell cycle-independent function of CDK4/6 in tumor immunosurveillance using small molecule CDK4/6 inhibitors (Palbociclib, Ribociclib, or Abemaciclib)." (PMID 30863749, 2019). "Along with biochemical and cellular assays carried out to assess its potency and selectivity, we demonstrate that combination with CDK4/6 inhibitors has a supra-additive effect on tumour cells." (PMID 30655555, 2019). "Combined inhibition of MET/FAK and CDK4/6 eliminates the proliferation capacity of cancer cells in culture, and enhances tumour growth inhibition in vivo." (PMID 31296956, 2019). "Next generation sequencing of circulating tumor DNA (ctDNA) in 34 patients after progression on CDK4/6 inhibitors identified FGFR1/2 amplification or activating mutations in 14/34 (41%) post-progression specimens." (PMID 30914635, 2019). "IHC staining revealed that up‐regulation of RN181 significantly increased the expression of p21 but dramatically reduced the expression of cyclin D1 and CDK4 in xenograft tumours of AGS cells (AGS‐RN181 versus AGS‐RV, all p < 0.01)." (PMID 30714150, 2019). "ES cells consequently have an activated cyclin D1/CDK4 pathway and require CDK4 and cyclin D1 for growth.In vivo data demonstrated decreased tumor growth and prolonged survival with CDK4/6 inhibition." (PMID 31031965, 2019). "In contrast to PD0332991 treatment which allowed tumor formation in a delayed manner, knockdown of CDK4 or CDK6 resulted in the inability of cells to form any tumor." (PMID 30858922, 2019). "Further stratified by tumour site, we report that primary tumours (n=80) were positive for CDK4 in 60.0%, for CDK6 in 85.0%, for p-Rb in 60.0%, and ≤10% for p16 in 37.5%." (PMID 30804704, 2019). "All 3 oncogenes in 50 CRCs, except for MYC in one tumor and CDK4 in three tumors, were upregulated and 3 normal colonic physiological genes were downregulated, except for CD177 in one tumor, AQP8 in two tumors and GPX3 in three tumors." (PMID 31409279, 2019). "It is important, therefore, to understand the molecular makeup of a tumor that has progressed on CDK4/6i treatment, in order to help inform subsequent treatment options." (PMID 31852484, 2019). "Both CDK inhibitors reduced cell proliferation in the DMOG tumours by 23% for both CDK4/6i and CDK1i." (PMID 31235824, 2019). "Although CDK4/6 inhibitor are effective in controlling tumor growth, a fraction of the cells acquire resistance to CDK4/6 inhibitors." (PMID 31178825, 2019).
tumor (continued). "Combination therapy strategies targeting these pathways with CDK4/6 inhibitors are synergistic and are being investigated in early phase multi-agent clinical trials in various tumor types." (PMID 31331377, 2019). "Recently, Goel and colleagues reported that cyclin-dependent kinases CDK4/6 inhibitors triggered anti-tumor immunity by upregulating the expression of genes involved in the process and presentation of peptide antigens." (PMID 31023256, 2019). "Most of them promote tumour development, e.g., cell cycle activators (c-Myc and CDK4/6), anti-apoptotic factor (Bcl2), activators of invasion (c-Met, Notch1 and Fra-1) and epithelial-mesenchymal transition inducing factor (SNAIL)." (PMID 31658284, 2019). "It has been reported that CDK4/6 inhibitors can effectively inhibit processes in tumor cells that lose endogenous inhibition of CDK4/6 because of P16 gene deletion." (PMID 31652270, 2019). "Second-generation selective CDK4/6 inhibitors, including palbociclib, ribociclib, and abemaciclib, can induce G1 phase cell cycle arrest in RB-positive tumor models with improved effectiveness and reduced adverse effects." (PMID 31652270, 2019). "We also explored the inhibitory effects of CDK4/6 inhibitors on PDX tumor growth containing normal or aberrant CDK4 pathway." (PMID 31358010, 2019). "In contrast to most targets of tumor-suppressive drugs (such as, for example, CDK4/6), very few tumor cell lines showed pronounced dependency on CDK8/CDK19/CCNC in DepMap analysis." (PMID 31382571, 2019). "It is worth noting that one recent study highlighted CDK4/6 knockdown reprograms metabolism in tumor cells, leading to Gln-addiction, which relies on c-Myc upregulation." (PMID 30899002, 2019). "The uncontrolled cellular proliferation of tumor cells often depends on the activity of the related kinases CDK4 and CDK6, and thus these kinases are targets for anti-tumoral drugs." (PMID 30692638, 2019). "Both proteins are tumor suppressors; p16 inhibits cyclin-dependent kinases 4 and 6 (CDK4 and CDK6) by phosphorylating the RB protein, thus preventing cell cycle progression." (PMID 31031965, 2019). "Deregulation of cyclin-dependent kinases 4 and 6 (CDK4/6) is highly prevalent in cancer; yet, inhibitors against these kinases are currently used only in restricted tumour contexts." (PMID 31296956, 2019). "It has been shown, however, that inhibition of CDK4/6 promotes anti-tumor immunity through several mechanisms." (PMID 31817861, 2019). "A combination of CDK4/6 inhibition (by ribociclib) with PI3Kα inhibition (by BYL719) showed the enhanced inhibition of tumor growth, as well as enhanced tumor immunogenicity and T cell activation in xenograft models of TNBC." (PMID 30959874, 2019). "We demonstrate the anti-tumor activity of elacestrant in multiple in vitro models of acquired CDK4/6i resistance that harbored either wild-type or mutant ERα and retained ER-driven tumor growth." (PMID 31852484, 2019). "In agreement with up‐regulation, down‐regulation of RN181 significantly decreased the expression of p21 but increased the expression of cyclin D1 and CDK4 in xenograft tumours of AGS cells (AGS‐KD versus AGS‐NC control, all p < 0.05)." (PMID 30714150, 2019). "In contrast, miR-34a has been identified as a tumor suppressor miRNA by repressing several target genes, such as cyclin-dependent kinase 4 (CDK4), CDK6, BCL2, MET, Notch, c-MYC, AXL and FOXP1." (PMID 31472685, 2019). "Restoring CDK4 in GC cells rescued the inhibitory phenotype produced by RN181 in vitro and in vivo, suggesting a dominant role of CDK4 in control of the tumour growth by RN181." (PMID 30714150, 2019).
tumor (continued). "Their common target IGF1R is a proto-oncogene, which is highly expressed in several tumor cells, CDK4 and CDC25A are proto-oncogenes." (PMID 31540229, 2019). "Nonetheless, barely connection was shown to interlink CDK4 expression with patient age, gender, tumor location, tumor volume or pathological grades." (PMID 30808351, 2019). "IHC staining of tumour sections confirmed the up‐regulation of RN181 (RN181 versus RV, p < 0.01) and CDK4 in both AGS‐RV tumour (RV + CDK4 versus RV, p < 0.01) and AGS‐RN181 tumour (RN181 + CDK4 versus RN181, p < 0.01)." (PMID 30714150, 2019). "Of these genes, only CDK4 occurred in the differential expression analyses, being underexpressed in CTNNB1-mutated tumours." (PMID 31000732, 2019). "CDK4/6 inhibitors do not only induce cell cycle arrest in tumor cells but are also capable of eliciting an anti-tumor immune response." (PMID 30959874, 2019). "Small molecule CDK4/6 inhibitors, such as palbociclib, elicit their anti-tumour effects in part by reinstating the G1/S checkpoint in tumour cells that still have the ability to express Rb; this often leads to cellular senescence." (PMID 30655555, 2019). "Studies have demonstrated an enhancement in the anti-tumor response upon treatment with CDK4/6 inhibitors due to an enhancement in interferon production, reduced T-regs and enhanced T cell activation." (PMID 31178825, 2019). "Driver events affecting CDK4 in a large proportion of our cases points to the potential therapeutic option of using CDK4 inhibitors to treat this tumor type." (PMID 31320640, 2019). "Recently, combination of PI3K inhibitor with CDK4/6 inhibitor has been shown to have a synergistic effect in tumor suppression in ER positive breast cancer." (PMID 31101835, 2019). "It was reported that inhibition of cell cycle components (CDK4/6) can trigger anti-tumor immune response." (PMID 31709193, 2019). "Targeting the ATP binding site of CDK4, Palbociclib was the first clinical approved anti-tumor CDK4 inhibitor." (PMID 30808351, 2019). "Our data validate MET/FAK signalling as a mechanism that enables CDK4/6-independent CDK2 activation and cell cycle transit, and we provide evidence for the utility of MET or FAK inhibition as a means to improve tumour response to CDK4/6 inhibition in vivo." (PMID 31296956, 2019). "Here we demonstrate that miR-34a exerted tumor-suppressive effects in HGSC by regulating the IL-6R/STAT3 signaling pathway and the associated expression of Snail, MMP9, CDK4, and survivin." (PMID 31448054, 2019). "CDK4/6 inhibition results not only in the pronounced reduction of cell proliferation but also in an impaired tumor angiogenesis." (PMID 30858922, 2019). "Together, these results provide evidence that MET activity constitutes a resistance mechanism in vitro and in vivo, reducing the tumour cell response to CDK4/6 inhibition." (PMID 31296956, 2019). "Chemical CDK4/6 inhibition decreases tumor growth and reduced angiogenesis, which is mimicked by shRNA mediated knockdown of either protein." (PMID 30858922, 2019). "We provide evidence demonstrating ER-driven tumor growth in a post-CDK4/6i tumor setting and preclinical rationale for the examination of elacestrant in patients that have progressed on a CDK4/6i." (PMID 31852484, 2019). "In TMA analysis, a high level of CDK4 relates to higher clinical stages and poorer patient prognosis, which indicates the necessity of CDK4 in tumor metastasis." (PMID 30808351, 2019). "Altogether, the results substantiate the role of the RN181–cyclin D1/CDK4 pathway in control of the tumour development of GC." (PMID 30714150, 2019). "CCND1 gene expression was highest in luminal A/B and lowest in basal-like tumours, while the opposite was true for CDK4/6 and the proliferation marker gene MKI67." (PMID 30819233, 2019).